ENSG00000212383
Synonyms: LOC124900330
Gene: Small nucleolar RNA gene on chromosome 12 (56,861,375 to 56,861,508, forward strand). Ensembl gene ENSG00000212383.
Gene Ontology:
Biological process: RNA processing
Cellular component: nucleolus
Homologues: Paralogues in human: SNORA48 (89% identical), SNORA48B (86% identical).